AIF1 (allograft inflammatory factor 1)
Diseases named in the same sentence as AIF1 in open-access papers (continued):
Sharing a sentence is not in itself a finding about the gene and the disease.
Obesity (continued). "Studies in human populations link sequence variants near the AIF1 locus with obesity and diabetes, but a potential role for AIF1 in the pathogenesis of these conditions has not been investigated." (PMID 36596796, 2023). "The function of AIF1 is not entirely known, but it has been found to be mainly expressed by immunocytes and closely associated with inflammatory diseases, obesity, diabetes and cancers." (PMID 30386176, 2018). "Allograft inflammatory factor 1 (AIF-1) is a putative obesity gene." (PMID 24267103, 2013). "Adipose AIF-1 is increased in obesity and might participate in the regulation of adipose tissue inflammation and, in turn, insulin resistance." (PMID 24267103, 2013). "Finally, to assess the potential relevance of this AIF1–MAOA axis to human obesity, we evaluated the expression of AIF1 and NE degradation pathway genes in discarded subcutaneous adipose tissues from participants with weight excess or obesity (BMI range 28.5–34.3)." (PMID 36596796, 2023). "It is unclear whether this reflects increased inflammation of adipose tissue in the high fat-fed mice (e.g. expression from increased amounts of inflammatory cells in the tissue), or whether this suggests that the role of Aif1 in obesity may be mediated via specific actions in adipose tissue." (PMID 22781276, 2012). "The potential relevance of AIF1-dependent catecholamine catabolism to human obesity is supported by the positive correlation of AIF1 with MAOA and ALDH1L2 transcript levels in adipose tissues from participants with weight excess or obesity." (PMID 36596796, 2023). "Targeting AIF-1 or AIF1-like (AIF1L) may yield novel strategies to mitigate disease progression and enhance clinical management of obesity." (PMID 41694567, 2026). "Finally, in adipose tissue from obese patients, AIF1 expression correlated with MAO-A expression, further supporting the link between AIF1 and MAO-A in NE catabolism in macrophages, obesity, insulin resistance and glucose intolerance." (PMID 39405979, 2024). "Here we show that male mice lacking the allograft inflammatory factor-1 (AIF1) protein resist high fat diet (HFD)-induced obesity and hyperglycemia." (PMID 36596796, 2023). "In addition, we provide evidence linking these findings to human obesity, in that AIF1 expression correlates positively with MAOA and ALDH1L2 levels in adipose tissues from individuals with weight excess or obesity." (PMID 36596796, 2023). "Based on these findings, in this project we aim to explore the potential function of AIF-1 in female adipose tissue by mapping AIF-1 expression and possible release from cells within adipose tissue, as well as its relationship to obesity and metabolic disturbances." (PMID 24267103, 2013). "Above all, HFD might increase the apoptosis of brown adipocytes via a non-classical apoptotic pathway, including AIF1, to weaken its anti-obesity effect." (PMID 25747866, 2015). "The AIF1 rs2844479 allele that associated with higher weight in the original GWAS was observed to associate with lower BMI in the present study, while the PTER and MAF SNPs did not associate with BMI or obesity in the present study." (PMID 23861046, 2013). "Male mice lacking AIF1 showed relative resistance to hyperglycemia and a high-fat diet, and their adipose-tissue levels of norepinephrine (NE) were higher, due to less monoaminoxidase A activity and NE clearance by macrophages, suggesting that AIF1 silencing protected against obesity." (PMID 37237507, 2023). "Levels of 5-HT in adipose tissues, liver, heart, and circulation were not suppressed by AIF1 deficiency, and serum levels of 5-hydroxyindoleacetic acid (5-HIAA), a major 5-HT metabolite, were unchanged —these findings argue against a role for peripheral 5-HT in the obesity resistance phenotype." (PMID 36596796, 2023).
Obesity (continued). "WT mice developed characteristic features of obesity that were not seen in Aif1−/− mice, and CT scanning revealed marked expansion of both subcutaneous and visceral adipose depots in HFD-fed WT mice also not found in HFD-fed Aif1−/− mice, or in mice of either genotype on standard chow diet (CD)." (PMID 36596796, 2023).
glioblastoma (31 papers, 2014 to 2025). The most malignant astrocytic tumor (WHO grade IV). "An early study in rat C6 glioblastoma and 9 L gliosarcoma tumor models and human astrocytomas found AIF1 expression in a distinct subset of tumor-associated activated macrophages/microglial cells that accumulated in specific areas of the tumor." (PMID 37237507, 2023). "The TCGA glioblastoma dataset was analysed for the expression of TSPO and SLC7A5 (=LAT1), encoding for the molecular targets of TSPO- and FET-PET, and for AIF1, as we found a high TSPO level in microglia and macrophages." (PMID 31963507, 2020).
colitis (24 papers, 2015 to 2025). Inflammation of the colon. "Since DSS-induced colitis is a good model to study CD in humans, we decided to evaluate the capacity of AIF-1 alone or in combination with CRP (a classical biomarker of the disease) to predict the severity of CD." (PMID 35327530, 2022). "Increased levels of AIF-1 in experimental colitis were confirmed by immunoblotting of AIF-1 in colon homogenates from DSS-treated animals and in serum samples." (PMID 35327530, 2022). "In this sense, it has been observed that mice that overexpress AIF-1 are more resistant to colitis induced by TNBS." (PMID 35327530, 2022). "In this study, we have demonstrated the presence of AIF-1 in the rat and human colon mucosa and that its expression increases in this intestinal region during experimental colitis or in Crohn’s disease, respectively." (PMID 35327530, 2022). "Furthermore, we recently demonstrated an increase in tissue levels of AIF-1 in rats with experimental colitis induced with DSS (dextran sodium sulfate), supporting its role in intestinal inflammation." (PMID 35327530, 2022).
breast cancer (22 papers, 2010 to 2025). A primary or metastatic malignant neoplasm involving the breast. "Another study used a mouse model of breast cancer metastases, and identified AIF1 upregulation in the metastasis-associated macrophages (MAMs) of metastatic breast cancer cells." (PMID 37237507, 2023). "Several studies have linked different roles of AIF1 with the development and pathogenesis of breast cancer." (PMID 37237507, 2023). "In patients with breast cancer, the expression of AIF-1 isoforms (variants) has been observed in breast adipose tissue monocytes and M1 macrophages." (PMID 32708725, 2020). "AIF1 has been demonstrated to reinforce the resistance of breast cancer cells to cisplatin by inhibition of cell apoptosis and reduction of intracellular cisplatin accumulation and AKAP12 is associated with paclitaxel-resistance in serous ovarian cancer." (PMID 36417130, 2023). "Subsequent studies also elucidated the fact that AIF1 promotes breast cancer cell migration through the activation of the p38 MAPK signaling pathway, which upregulates the expression of tumor necrosis factor-α (TNF-α)." (PMID 37237507, 2023). "Studies have also found that AIF-1 plays a major role in infiltrating immune cells and mediating tumor progression, implying its high potential as a target molecule for breast cancer diagnosis, prognostication, and treatment." (PMID 37014322, 2023). "Open Science Framework: Raw data for "Induction of interferon signaling and allograft inflammatory factor 1 in macrophages in a mouse model of breast cancer metastases".10.17605/OSF.IO/42T98." (PMID 33824914, 2021). "AIF-1 v.1 expression correlates with anthropometric parameters in patients with breast cancer, and v.3 is the longest isoform, which is also called the “wild type”." (PMID 32708725, 2020). "Furthermore, overexpression or silencing of AIF1 in the breast cancer cell line MDA-MB-231 led to enhanced and decreased proliferation, respectively." (PMID 37237507, 2023). "AIF-1 has been shown to promote proliferation and migration of breast cancer cells, and whilst its role in HCC remains unknown, increased mRNA levels in HCC tumor cells have been observed." (PMID 32374744, 2020). "Similarly, Aif1 expressionis highly-upregulated in the tumor stroma of human breast cancers (See SupplementaryTable 1; p = 8.35 x 10-24)." (PMID 20442453, 2010). "However, AIF1 deficiency in MAMs did not affect the number of lung metastases; therefore, the role of AIF1 in the metastasis of breast cancer cells seems to be limited to the activation of MAMs." (PMID 37237507, 2023).
dementia (21 papers, 2014 to 2026). Loss of intellectual abilities interfering with an individual's social and occupational functions. "This is considered to have more specificity for activated microglia than AIF-1 and has been reported as generally elevated in AD and correlated with AD plaque stage and clinical dementia rating, although only one previous mRNA study, in hippocampal tissue, was identified." (PMID 34828359, 2021).
schizophrenia (20 papers, 2017 to 2025). A major psychotic disorder characterized by abnormalities in the perception or expression of reality. "However, increased AIF1, CD68, and TSPO mRNA was identified in high immune schizophrenia cases, although the number of microglia per se seemed unchanged." (PMID 31168068, 2021).
tauopathy (20 papers, 2018 to 2026). Neurodegenerative disorders involving deposition of abnormal tau protein isoforms (tau proteins) in neurons and glial cells in the brain. "Furthermore, within the tauopathy mouse model, we found a strong association between CXCR4 and TMEM119 and AIF1 within the hippocampus." (PMID 29636460, 2018).
rheumatoid arthritis (15 papers, 2012 to 2026). A chronic, systemic autoimmune disorder characterized by inflammation in the synovial membranes and articular surfaces. "For example, AIF1, MICA, ATF6B, and HSPA1L were found to be associated with an increased risk of rheumatoid arthritis (RA), while AIF1 was also associated with an increased risk of atopic dermatitis." (PMID 38835753, 2024). "Several subsequent studies have linked AIF1 with inflammation, immunoinflammatory diseases such as kidney disease, rheumatoid arthritis, cancer or cardiovascular disease and transplant rejection." (PMID 37237507, 2023). "Relevant studies have linked AIF1 with inflammatory diseases such as kidney disease, rheumatoid arthritis, cancer, cardiovascular diseases (CVDs), neurological disorders and transplants." (PMID 37237507, 2023). "Due to its multiple functions, AIF1 is linked with the activation of macrophages and several diseases such as kidney disease, rheumatoid arthritis, cancer, cardiovascular diseases, metabolic diseases, neurological disorders and transplants." (PMID 37237507, 2023). "Similarly, the AJ population has a reduced frequency of the R15W variant of the AIF1 gene, which has been strongly (odds ratio > 2) associated with rheumatoid arthritis." (PMID 22277159, 2012). "Previous studies have linked AIF1 to various autoimmune diseases, including anti-GBM nephritis, rheumatoid arthritis, autoimmune rat nervous system lesions, and cardiac allograft rejection." (PMID 38475831, 2024). "AIF1 plays important roles in the development of several diseases: kidney disease, rheumatoid arthritis, cancer, cardiovascular diseases, metabolic diseases and neurological disorders, and in transplants." (PMID 37237507, 2023). "Another positive regulator of inflammatory response found in the gene profile was Aif1, which is known to be highly expressed in synovial tissues of rheumatoid arthritis patients." (PMID 32371954, 2020). "AIF-1 is the molecule involved in the pathogenesis of diseases with chronic inflammatory response, especially those involving macrophages, such as rheumatoid arthritis." (PMID 32708725, 2020). "The role of AIF-1 in rheumatoid arthritis and systemic sclerosis has been investigated and the rs2269475 SNP was found associated with an increased risk of developing both diseases." (PMID 30252881, 2018). "An extensive body of work could demonstrate the involvement of AIF1 in various disease conditions ranging from rheumatoid arthritis, systemic sclerosis, encephalomyelitis to cancer." (PMID 30001384, 2018). "AIF1 plays a critical role in the regulation of massive synovial proliferation and the production of IL6 in rheumatoid arthritis." (PMID 32110485, 2020). "In this study, we examined the expression of AIF-1 isoforms on the level of mRNA, and we compared the percentage of AIF-1-positive white blood cells (WBCs) in blood and AIF-1/CD68 cells in the synovial membranes in patients with rheumatoid arthritis (RA) and osteoarthritis (OA)." (PMID 32708725, 2020).
prion disease (14 papers, 2013 to 2026). A transmissible disease that is caused by a protein that is able to induce abnormal folding of normal cellular proteins, leading to characteristic spongiform brain changes, which are associated with neuronal loss without an inflammatory response. "Analysis of the correlation of these neuropathological markers of CNS prions disease (AIF1 + microglia; CD44+ and GFAP+ astrocytes; PrPd) showed the variance across all the prion agent strain/recipient mouse combinations studied." (PMID 31551718, 2019). "The characteristic neuropathological signs of prion disease including spongiform pathology (vacuolation), PrPd accumulations, microglial activation (AIF-1 + cells) and reactive astrocytosis (GFAP + cells) were detected in the brains of all the clinically-affected mice from each group." (PMID 31836813, 2019). "In addition, we analysed Sirpa, Cd47, Aif1, Trem2 and Mfge8 mRNA levels selectively in hippocampus and cerebellum at different time points during the progression of prion disease using RNA sequencing." (PMID 28545141, 2017). "Interestingly, Aif1+Ftl1+ microglia corresponded morphologically dystrophic iron-accumulating microglia in an Alzheimer’s mouse model, possibly providing clues as to the role of phagocytic microglia in prion disease." (PMID 36352465, 2022).
melanoma (13 papers, 2019 to 2025). A malignant, usually aggressive tumor composed of atypical, neoplastic melanocytes. "High methylation levels of AIF-1 were associated with a worse prognosis in UCEC and melanoma, whereas they were associated with a better prognosis in GBM, KIRC, OV, and UVM." (PMID 37014322, 2023). "Cd74/C1q/Aif1-expressing macrophages also are characterized by higher expression of the complement components C1qa and C1qb, which have been positively correlated with immune cell infiltration, apoptosis, and improved survival in previous studies of melanoma." (PMID 41122966, 2025). "Conversely, hypomethylation of AIF-1 is linked with a favorable prognosis in UCEC and melanoma." (PMID 37014322, 2023). "Surprisingly, our findings revealed that hypomethylation of AIF-1 resulted in shorter life durations in GBMLGG, KIRC, OV, and UVM; however, hypermethylation of AIF-1 resulted in shorter life durations in UCEC and melanoma." (PMID 37014322, 2023).
brain tumor (12 papers, 2011 to 2025). "It is also important to mention that our recently developed highly invasive VM3 mouse brain tumor cells are of myeloid origin and are highly positive for AIF1/Iba1 by gene and protein expression." (PMID 21479220, 2011). "It was not known if CR could reduce the AIF1/Iba1 expression in brain tumors." (PMID 21479220, 2011).
Hyperglycemia (11 papers, 2013 to 2023). An increased concentration of glucose in the blood. "In this study, it was demonstrated that AIF-1 regulated the levels of miR-34a, ATG4B, autophagy, inflammation, and oxidative stress in glomerular endothelial cells induced by hyperglycemia via in vivo and in vitro studies." (PMID 36345369, 2022). "With HFD feeding, glucose levels in both WT and Aif1−/− mice were higher than with CD; however, mice lacking AIF1 and fed with either CD or HFD showed relative protection against hyperglycemia." (PMID 36596796, 2023).
ZIKV infection (11 papers, 2017 to 2026). "We found that the expression of a panel of genes known to be specifically induced by microglial activation, including Clec7a, Aif1, Gfap, and Trem2, was significantly increased upon ZIKV infection." (PMID 39273400, 2024).
brain inflammation (9 papers, 2018 to 2025). "To evaluate brain inflammation, we examined the expression of TNF-α and the activation of allograft inflammatory factor 1 (Iba1)." (PMID 37950725, 2023).
astrocytoma (8 papers, 2011 to 2022). "The results of Western blot analysis illustrate that CR significantly reduced expression of AIF-1 in total protein lysates of the CT-2A astrocytoma." (PMID 21479220, 2011). "We found that the anti-inflammatory effects of CR in the CT-2A astrocytoma were associated with (i) reduced nuclear NF-κB activation and subsequent DNA binding to promoters of proinflammatory genes, (ii) reduced COX-2 and AIF-1 expression, (iii) reduced CD68 and MIP-2 expression." (PMID 21479220, 2011).
experimental autoimmune encephalomyelitis (8 papers, 2018 to 2026). An autoimmune demyelinating disease of the central nervous system that is produced experimentally in animals by the injection of homogenized brain or spinal cord in Freund's adjuvant. "Mouse models and in vitro studies display a significant role for AIF1 in autoimmune diseases such as experimental autoimmune encephalomyelitis (EAE), animal model of multiple sclerosis, neuritis, and type 1 diabetes in non-obese diabetic mice." (PMID 32107417, 2020). "Another study of experimental autoimmune encephalomyelitis (EAE), neuritis, and uveitis in rats showed that there were AIF1-expressing macrophages within autoimmune lesions and AIF1-expressing microglia in the injured brain." (PMID 37237507, 2023).
atherosclerosis (7 papers, 2020 to 2025). A disease characterized by the build-up of fatty material and calcium deposition in the arterial wall resulting in partial or complete occlusion of the arterial lumen. "The pro-inflammatory molecule, AIF1, is also associated with the development of atherosclerosis and is expressed primarily in the monocyte/macrophage (MP) lineage, and is a positive regulator of the NF-κB pathway." (PMID 36247468, 2022). "AIF-1 is also considered as a new risk factor for the development of atherosclerosis, and, when overexpressed, it influences the intensification of atherosclerotic plaque calcification." (PMID 33114451, 2020). "AIF1 appears to be involved in the development of atherosclerosis." (PMID 37237507, 2023). "Previous studies showed that inhibition of AIF-1 protein expression in ECs and VSMCs could alleviate atherosclerosis." (PMID 35937793, 2022). "And the increased level of AIF-1 in VSMCs, induced by external stimulation, could also enhance the expression of cyclin and skeleton protein, thus leading to cell migration and phenotypic transformation, atherosclerosis, and vascular inflammation." (PMID 35937793, 2022). "Allograft inflammatory factor 1 (AIF1) plays an important role in the occurrence and progression of atherosclerosis by stimulating the migration and proliferation of human smooth muscle cells and promoting the activation of macrophages." (PMID 36602538, 2023).
status epilepticus (7 papers, 2014 to 2024). Status epilepticus is defined as a continuous seizure lasting more than 30 min, or two or more seizures without full recovery of consciousness between any of them. "Pre-treatment with Tualang honey reduced neuroinflammation by reducing the elevation of TNF-α, IL-1β, glial fibrillary acidic protein, allograft inflammatory factor 1 and COX-2 in the cerebral cortex, cerebellum and brainstem of kainic acid-induced status epilepticus rat." (PMID 33435215, 2021).